BRAF (B-Raf proto-oncogene, serine/threonine kinase)
Diseases named in the same sentence as BRAF in open-access papers (continued):
Sharing a sentence is not in itself a finding about the gene and the disease.
melanoma (continued). "Consequently, the recommended treatment approach for patients with advanced or metastatic BRAF-mutated melanoma is now a combination of a BRAF inhibitor and a MAPK kinase (MEK) inhibitor." (PMID 33003483, 2020). "Approximatively 45% of patients (n = 13) had BRAF mutated melanoma." (PMID 32947841, 2020). "In BRAF-mutated melanoma, the response rate to BRAF and MEK inhibition was 67–69% and 68–70% with first-line dabrafenib + trametinib and vemurafenib + cobimetinib, respectively; and 63% with encorafenib + binimetinib in previously untreated patients or who progressed after previous ICI." (PMID 32585901, 2020). "Therefore, melanoma, which is caused by BRAF gene mutation, was taken as an example to verify our model." (PMID 33084582, 2020). "BRAF p.V600E variant increases the growth and spread of cancer cells and, although, in some types of cancer, such as melanoma or non-small cell lung cancer, BRAF inhibitors have clinical activity in the V600E variant, these inhibitors alone have limited activity in BRAF V600E-mutated CRC." (PMID 32933095, 2020). "FDA approved this therapeutic association for the treatment of BRAF-mutated melanoma and NSCLC." (PMID 33292371, 2020). "Finally, in concordance with Dabrafenib’s intended use in treatment of BRAF mutation-positive melanomas and lung cancers, the skin tissue feature is the third most predictive one for the best OT + S RF model." (PMID 32523056, 2020). "BRAF testing is currently recommended by both the National Comprehensive Cancer Network (NCCN) and the European Society for Medical Oncology (ESMO) guidelines for advanced melanoma patients; the BRAF V600 mutation must be detected by using an FDA-approved (USA) or CE-IVD-certified (Europe) test." (PMID 32751423, 2020). "A higher incidence of mutated BRAF is found in melanoma than in CRC." (PMID 32296018, 2020). "A total of 32 patients had a BRAF-mutated melanoma and 36 had an NRAS mutation." (PMID 32664549, 2020). "Similarly, in another recent work, researchers compared ddPCR with Sanger sequencing and pyrosequencing in 40 melanoma FFPE tissues regarding the detection rates of mutations in BRAF, NRAS, and TERT promoter." (PMID 32695793, 2020). "A mutation in the kinase BRAF is observed in approximately 50% of melanomas." (PMID 32414111, 2020). "Later, FDA approved Trametinib, which is different from the first two in that it is a MEK inhibitor, and the MEK and mutant BRAF share a partially overlapping signaling pathway, the MEK inhibitors can also be used in the treatment of BRAF mutation of melanoma patients." (PMID 33344444, 2020). "This hypothesis is supported by a clinical phase III trial that reported a significantly decreased recurrence of completely resected, stage III melanoma with BRAF-V600E or -V600K mutations treated with a combination of BRAF and MEK inhibitors after surgery." (PMID 32626653, 2020). "Additionally, in lung adenocarcinoma and melanoma, 3–6% and 0.14–3% of the BRAF mutant cases harbor concomitant PI3KCA mutation, respectively." (PMID 33081092, 2020). "BRAF gene mutation (BRAF V600E) is directly related to the occurrence of melanoma." (PMID 33330635, 2020). "First, our study does not change available data suggesting that MEK inhibition may be still considered for melanoma patients whose tumors harbor class 2 BRAF mutations, or perhaps non-small cell lung cancer patients." (PMID 33216832, 2020). "Tumors with BRAF mutations could respond to BRAF kinase inhibitor vemurafenib that was approved by the FDA in 2011 for therapy of patients with advanced melanoma and late-stage (metastatic) melanoma." (PMID 30925905, 2019). "Binimetinib has shown promising results in BRAF-mutated melanoma, both alone and in combination." (PMID 30956763, 2019).
melanoma (continued). "Binimetinib showed activity in patients with BRAF- or NRAS-mutated melanoma through MAPK pathway inhibition, and genomic profiling highlighted genetic alterations of interest that could be used as potential predictive biomarkers of response to binimetinib." (PMID 30956763, 2019). "As loss of FBW7/USP28 enhances the expression of all three RAF family members, melanoma cells harbouring mutations in this complex may require the activity of both BRAF and CRAF for tumour progression." (PMID 31416288, 2019). "Indeed, the antitumor effects of the combination of phenformin with PLX4720, a BRAF inhibitor, on the proliferation of BRAF-mutated melanoma both in vitro and on tumor growth promoted by BRAF in vivo have been investigated." (PMID 31284513, 2019). "In addition to other mechanisms, a typical mechanis of resistance is mediated by ERK1/2 hyperactivation in melanoma cells including amplification of BRAF expression, and/or mutational activation of MEK13." (PMID 31578454, 2019). "With this systematic review and meta-analysis, we set out to clarify the type, incidence, and relative risk of CVAEs in patients with melanoma who are being treated with a combination of BRAF and MEK inhibitors compared with patients receiving BRAF inhibitor monotherapy." (PMID 31397860, 2019). "The selection of mutational targets for ctDNA analysis was based on the following criteria: (a) known melanoma hotspot mutation in BRAF, NRAS, and/or TERT promoter; (b) COSMIC/TCGA reported mutation; (c) other mutation with a polyPhen score >0.7 and high variant allele frequency (VAF) in the tumor." (PMID 30312528, 2019). "BRAF mutational status in these two melanoma cell lines was confirmed by direct sequencing." (PMID 30254376, 2019). "A second mutation causing the loss of a tumor‐suppressor gene or causing a second mutation could cause a transition from ‘benign’ BRAF‐mutated nevi to malignant melanoma." (PMID 30499222, 2019). "The peculiar NRAS and BRAF mutation spectra in mucosal melanomas could also be linked to different oncogenic potencies as well as distinct cell-specific functional consequences." (PMID 31398831, 2019). "Among these, activating BRAF mutations occurs in 50% to 60% of melanomas." (PMID 31374895, 2019). "Notably, BRAF mutations are quite infrequent in mucosal melanomas (5% of cases, compared to 15% of NRAS and 26% of c-KIT mutations)." (PMID 30934534, 2019). "Only about half of all melanomas have a mutation in the BRAF gene, and, therefore, compound 1, targeting both BRAF-mutant and WT melanoma cells, may have a broader clinical impact." (PMID 30691132, 2019). "Combination therapy in adults with BRAF mutated melanoma has yielded higher objective response rates, prolonged survival rates, decreased rates of resistance, and decreased incidence of side effects most notably skin toxicities when compared to BRAF inhibitor monotherapy." (PMID 30728904, 2019). "Altogether, this might provide rationale for future studies investigating potential pathophysiologic connections between immune checkpoint expression, among them TIM-3, and BRAF mutations, or BRAF inhibition in melanoma." (PMID 31747929, 2019). "TERT promoter mutations have been shown to correlate with poorer outcomes in subsets of melanoma patients with BRAF/NRAS mutations, and this may serve as a potential future biomarker." (PMID 31861163, 2019). "A variety of recurrent BRAF mutations were detected in melanomas in a clinical diagnostics setting." (PMID 31277584, 2019). "Acral melanoma characteristically has a different genetic background compared with other subtypes (e.g., infrequent BRAF mutations and frequent KIT mutations), and mechanical stress (rather than ultraviolet irradiation) may be a causative factor." (PMID 31817947, 2019).
melanoma (continued). "In three melanoma cell lines that harbored the BRAF V600E mutation (A375, M229 and M238), treatment of the cells (24 h) with either the BRAF inhibitor vemurafenib (PLX4032) or a MEK inhibitor (U0126) significantly downregulated the LNK mRNA and protein expression." (PMID 31110180, 2019). "In addition, there are targeted therapies (BRAF/MEK inhibitors) available as a treatment for patients with BRAF-mutated melanomas." (PMID 31111349, 2019). "Indeed, A375-M6 melanoma cells are BRAF mutated (V600E) and when they are adapted to an acidic medium they acquire an enhanced activation of PI-3 kinase-AKT pathway crucial for vemurafenib resistance development, as we have previously demonstrated." (PMID 31275384, 2019). "Hence, there is a clinical need to identify biomarkers that can allow accurate identification of the best treatment approach in the individual patient with BRAF-mutated melanoma." (PMID 31730502, 2019). "In conclusion, we provide a basis for a strategy that may overcome the radioresistance of BRAF-mutated melanoma cells to radiotherapy." (PMID 31374895, 2019). "In a phase III trial (COMBI-I), which evaluated dabrafenib, trametinib and PDR001, an anti-PD-1 antibody, in patients with advanced BRAF-mutated melanoma, preliminary results show that all nine patients responded (33% complete responses and 67% partial responses)." (PMID 31340499, 2019). "Very importantly, the tumor microenvironment, namely melanoma associated fibroblasts, were activated by BRAF inhibition inducing FAK-dependent melanoma survival and a combination of Vemurafenib with a FAK inhibitor lead to tumor regression in mouse allografts and patient-derived xenografts." (PMID 30728057, 2019). "Furthermore, the levels of selected lncRNAs appeared to be linked with primary progression to BRAF inhibitor in melanoma patients." (PMID 31231466, 2019). "SRF/MRTF inhibitors could present an attractive approach to tackling BRAF inhibitor resistance in melanoma caused by RAC1P29S compared with the use of RAC inhibitors, which have to date proved difficult to progress into the clinic." (PMID 31257073, 2019). "These occur in 20–30% of melanoma patients and are mutually exclusive with BRAF mutations, except in resistant melanomas after targeted therapy, which may harbor co-occurring BRAF and NRAS mutations." (PMID 31635389, 2019). "Mutations of BRAF are found in about 65% of melanomas, while about 20% carry NRAS mutations." (PMID 31480477, 2019). "Certain genetic mutations can affect melanoma patients’ prognoses, such as the BRAF gene mutation." (PMID 31890008, 2019). "The 30% of melanoma patients with PTEN loss often presented a V600E BRAF point mutation." (PMID 31500143, 2019). "Finally, our analysis showed significant correlations between HAVCR2/TIM-3 methylation status (in both the promoter area and gene body) and BRAF-mutational subtype in melanoma." (PMID 31747929, 2019). "Moreover, overexpression of BRAFV600E and splicing variants of BRAF have been observed in melanoma or lung cancer upon acquired resistance." (PMID 31426419, 2019). "The observations above suggest that changes in the level of expression of selected miRNAs could allow distinguishing BRAF-mutated melanomas after development of resistance to inhibitors of the MAPK pathway." (PMID 30254376, 2019). "Considering that drug resistance is one of the main factors limiting the efficacy of melanoma therapy, the BRAF-mutated-A375 human melanoma cell line was cultured with gradually increasing concentrations of dabrafenib until a cell subpopulation grew in the constant presence of 5 μM of this drug." (PMID 31783660, 2019). "That BRAF inhibition might be effective in BRAF mutated tumors outside of melanomas is supported in this study." (PMID 30847023, 2019).
melanoma (continued). "Intriguingly, accompanied by reduced 14–3–3 binding, BRAF p-S365 phosphorylation was significantly downregulated in melanoma cells treated with TNFα, suggesting that K27-linked ubiquitination of BRAF may facilitate the dephosphorylation of p-S365." (PMID 31015455, 2019). "The emerging importance of targeted therapy approaches in oncology together with the established role of BRAF mutation specific small molecule inhibitor treatment in metastasized melanoma have laid the foundation upon which the transfer to other tumor entities with BRAF alterations can be built." (PMID 31181803, 2019). "By this approach, two melanoma samples with a mutation at very low frequency in the BRAF gene, missed both by mass-spectrometry and Sanger sequencing, were correctly identified, confirming the high sensitivity of NGS method comparable to the previous screening by competitive allele-specific PCR." (PMID 31547467, 2019). "In this context, preclinical studies suggest a phenformin and BRAF inhibitor combination may be more effective than a single-agent BRAF inhibitor to treat patients with BRAF-mutated melanoma." (PMID 31284513, 2019). "Similarly, in syngeneic mouse models of BRAF V600E-mutated melanoma, PLX-3397 combination therapy with adoptive cell transfer immunotherapy, showed reduction in TAMs and increase in tumor infiltrating lymphocytes leading to increased release of IFN-γ." (PMID 31439034, 2019). "BRAF V600E mutations often co-occur in melanoma and thyroid cancer with TERT point mutations." (PMID 30709063, 2019). "However, resistance to BRAFi frequently develops in BRAF‐treated melanoma patients and is linked to increased dissemination of these tumours." (PMID 30582770, 2019). "Interestingly SRC has been implicated in BRAF inhibitor resistance in BRAF‐mutant melanoma cells and patient‐derived tissues." (PMID 30979792, 2019). "Several studies have reported that melanoma cells carrying active BRAF mutations are able to increase secretion of immunosuppressive cytokines, lower expression of tumour-associated antigens, and upregulate checkpoints ligands as PD-L1/L2, leading to the suppression of T-cell activities." (PMID 31581559, 2019). "In order to assess in greater detail this aspect we conducted the present study in a panel of V600 BRAF-mutated human melanoma cell lines and utilizing a combination of approaches involving the use of conditioned medium from BRAFi exposed cells and of neutralizing antibodies against NRG1." (PMID 31557826, 2019). "The approach has been used in BRAF-mutated melanoma and was found to be superior to surgery alone." (PMID 31319771, 2019). "Given the potential clinical utility of BDX008 for optimization of advanced melanoma treatment, we sought to further validate the test in an independent cohort of patients with known BRAF mutation status treated with anti-PD-1 therapy in an unselected population previously treated with ipilimumab." (PMID 30925943, 2019). "In melanomas, the ‘V600E’ mutation in the BRAF gene is the most commonly observed mutation." (PMID 30582770, 2019). "At least 50 % of melanomas harbor a V600E mutation in the BRAF gene." (PMID 30925905, 2019). "In melanoma, the concordance of BRAF mutations is 80.00% (52/65)." (PMID 31650022, 2019). "It has been reported that molecular diagnosis for guiding targeted therapies, such as KRAS and BRAF mutation test in colorectal cancer, HER-2 amplification test in breast cancer, and BRAF mutation test in melanoma, become more and more important in cancer management." (PMID 31136302, 2019). "Importantly, in advanced melanoma, oncogenic BRAF and NRAS mutation can modulate EMT through the MEK/ERK/FRA-1 pathway." (PMID 31514305, 2019). "BRAF is a serine-threonine protein kinase mutated in almost the 50%–60% of melanomas mostly harbouring the mutation V600E that increases the protein kinase activity, the consequent activation of the BRAF/MAPK/ERK signalling pathways and therefore the tumour cell growth and proliferation." (PMID 31801187, 2019).
melanoma (continued). "The FDA approved dabrafenib plus trametinib for the anaplastic thyroid cancer (ATC) with BRAF-V600E mutation in May 2018, as well as for the adjuvant treatment of BRAF V600E/K-mutated melanoma in April 2018." (PMID 31058077, 2019). "BRAF V600 mutation presents a potential prognostic predictor in melanoma." (PMID 31890008, 2019). "In clinical settings, whether a melanoma has BRAF mutations is a major concern, because the patients’ BRAF status influences the treatment strategy." (PMID 31817947, 2019). "The Idylla BRAF Mutation Assay has been shown to be efficient for testing FFPE melanoma samples." (PMID 31415669, 2019). "Furthermore, hTERT promoter mutations are also closely associated with FGFR3 mutations in BC, or with BRAF/NRAS mutations in melanoma or papillary thyroid carcinoma (PTC)." (PMID 31186051, 2019). "In addition, circulating IGF2as was identified as an independent factor for BRAF-mutated advanced melanoma prognosis in patients receiving vemurafenib." (PMID 31231466, 2019). "We propose that the tissue-specific interplay between ncRNAs might partly explain the different sensitivity to BRAF inhibitors in colon adenocarcinoma and melanoma harboring the same oncogenic mutation in BRAF." (PMID 31001323, 2019). "In addition, mutation of the serine/threonine kinase BRAF is found in almost 50% of the malignant melanoma patients; in more than 90% of the cases BRAF harbors V600E point mutation." (PMID 31370278, 2019). "Moreover, the BRAF mutation spectrum in mucosal melanoma is closely related to the mutation spectrum seen in lung cancers where mutations are often associated with the genotoxic effects of cigarette smoking." (PMID 31398831, 2019). "Because ERK lies downstream of KRAS, EGFR cannot induce permanent inhibition in pancreatic cancer, but MEK1/2 inhibitors, which target downstream of KRAS and upstream of ERK, have been approved by the FDA for BRAF mutated melanoma and are being tested in many other cancers." (PMID 30921351, 2019). "MEK and ERK mutations are rare, but almost 8% of all human cancers, including colorectal cancers (10%), papillary thyroid carcinomas (45%), serous ovarian tumors (~30%), non-small cell lung cancers (NSCLCs) (5–10%) and melanomas (>50%) harbor an activating somatic mutation in the BRAF oncogene." (PMID 31581557, 2019). "Moreover, although treatment with Vemurafenib of Dabrafenib produces some clinical benefit in nearly all patients with BRAF mutated melanomas, more than 90% of them develop resistance to these drugs within one year." (PMID 31762942, 2019). "Along these lines, we set out to more deeply characterize the mechanism(s) which proscribe the concurrence of BRAF(pV600E) and NRAS(pQ61) mutations in melanoma with an eye towards novel pathways which could countermand constitutive BRAF or NRAS signaling." (PMID 30651601, 2019). "Several patients with BRAF mutations had amplification of genes on chromosome 7q; these patients tended to have shorter progression-free survival than other patients with BRAF-mutant melanoma." (PMID 30956763, 2019). "Furthermore, gene set enrichment analysis (GSEA) of multiple independent datasets revealed that BRAFi treatment of BRAF-mutant melanomas caused a significant increase in the expression of the autophagy–lysosome gene set." (PMID 30979895, 2019). "Sequencing and BRAF inhibitor therapy changed the course of the disease for metastatic patients, as BRAF mutation is one of the key targetable genetic aberrations that occurs in melanomas." (PMID 30900145, 2019). "In addition, there is a well-known repertoire of common driver mutations in melanoma, with the most prevalent being mutations in BRAF, NRAS." (PMID 31649871, 2019). "The role of pembrolizumab in advanced melanoma was explored in the Phase 1 KEYNOTE-001 trial, in which patients with advanced or unresectable melanoma who had previously failed treatment with ipilimumab and a BRAF inhibitor (if BRAFV600-mutated) were treated with pembrolizumab." (PMID 31205619, 2019).